CD5 (CD5 molecule)
Diseases named in the same sentence as CD5 in open-access papers (continued):
Sharing a sentence is not in itself a finding about the gene and the disease.
leukemia (72 papers, 2008 to 2025). A malignant (clonal) hematologic disorder, involving hematopoietic stem cells and characterized by the presence of primitive or atypical myeloid or lymphoid cells in the bone marrow and the blood. "In contrast, CLL is a lymphoid malignancy with progressive accumulations of mature monoclonal CD5+ B lymphocytes and accounts for 37% of leukemia cases in adults older than age 19 years, making it the most common leukemia in the USA." (PMID 40656411, 2025). "Chronic lymphocytic leukemia/small lymphocytic lymphoma (CLL/SLL) is a common leukemia characterized by clonal expansion of mature CD5+/CD23 + B cells in the blood, bone marrow (BM) and lymphoid tissues." (PMID 39052034, 2024). "To explore the effectiveness of PNA treatment, we chose to use the human T-leukemia Jurkat cell line due to its high and more stable expression of CD5 compared to the few commercially available B-CLL cell lines." (PMID 35358273, 2022). "One early paper compared CD5+ leukemic cells with CD5− normal B cells in the same patient and found that leukemia cells had increased levels of MHC-I, which would inhibit NK cell cytotoxicity." (PMID 36497266, 2022). "The development of leukemia was evaluated by regular flow cytometric analysis of human CD5 and CD7 T-ALL markers on peripheral blood." (PMID 33947863, 2021). "These researchers concluded that 4-1BB-based CD5-redirected CAR-Ts equipped with the Tet-Off system demonstrated superior and more prolonged leukemia repression in comparison with CD28-based CD5-redirected CAR-Ts in preclinical xenograft models." (PMID 34620233, 2021). "Chronic lymphocytic leukemia (CLL) is the most prevalent adult leukemia in Western societies, characterized by clonal expansion of mature CD5+/CD19+ expressing B lymphocytes with significant genetic and clinical heterogeneity." (PMID 33451349, 2021). "Three weeks after the start of treatment, mice receiving ND2158 showed a significant decrease in absolute counts of CD19+CD5+ leukemia cells in PB compared to vehicle-treated controls." (PMID 31197259, 2020). "In combination with other immunophenotypic parameters of leukemia cells, including CD5 and CD23, they also allow for a more detailed evaluation of the effectiveness of therapy and its further monitoring at the level of minimal residual disease (MRD)." (PMID 33147729, 2020). "CD5 CAR T cells had robust cytotoxicity against CD5+ T-cell lines and primary tumor cells in vitro and protected mice from systemic leukemia progression in two xenograft models of human T-ALL." (PMID 30891427, 2019). "Flow cytometry analysis showed that the EMC cell lines maintained the CD5+CD43+IgM+CD19+ phenotype of the primary leukemia, even after prolonged (at least 22 weeks) in vitro culture." (PMID 29069762, 2017). "This leukemia is characterized by a slow accumulation of mainly quiescent clonal CD5 positive B cells that infiltrates secondary lymphoid organs, bone marrow and peripheral blood." (PMID 29206143, 2017). "Chronic lymphocytic leukemia (CLL), the most common adulthood leukemia, is characterized by the accumulation of abnormal CD5+ B lymphocytes, which results in a progressive failure of the immune system." (PMID 25734483, 2015). "To characterize the underlying mechanism involved in the cooperative effect between lenalidomide and rituximab, we analyzed the effect of lenalidomide on CD20 expression on leukemia cells (CD5+/CD19+) after 2, 7, and 14 days of treatment." (PMID 25313353, 2014). "B-chronic lymphocytic leukemia (B-CLL), the most common human leukemia, involves the accumulation of predominantly quiescent CD5+ B cells driven by the proliferation of a subpopulation." (PMID 23555960, 2013). "Anti-CD5 ITs have been devised as a tool for the therapy of T-cell lymphomas and leukemias and CD5+ B-chronic lymphocytic leukemia (B-CLL)." (PMID 22069735, 2011).
leukemia (continued). "In FCM, T-LGL leukemia cells revealed abnormal expression of CD5, CD7, and CD43 antigen, which corresponds to the findings of Lundell and colleagues." (PMID 18474096, 2008). "Although we were unable to directly correlate E1B upregulation in leukemia with aging, previous studies have shown that aging and leukemia share key features of immune dysregulation, including altered T-cell function and changes in CD5 expression." (PMID 40788503, 2025). "However, if more than 75% of leukemic cells express CD5 but retain the other immunophenotypic criteria, the leukemia in this case is called near ETP-ALL." (PMID 39553118, 2024). "We found high levels of Ki67 in CD19+CD5+ murine leukemia cells from the PB and spleen while leukemic cells in the BM expressed significantly lower levels of ki67, suggesting that in this mouse model, proliferating cells are not sequestered in the BM compartment." (PMID 39691453, 2024). "However, starting from day 18th after TCL1 leukemia inoculation, we detected a significant decrease in the percentage of leukemic cells (CD5+CD19+), in the peripheral blood, of DT-treated mice as compared to untreated TCL1 leukemia-bearing animals." (PMID 35296093, 2022). "In the second part, we used an immortalized human leukemia T-cell line (Jurkat cells), which stably expresses the CD5 protein at high levels, and peripheral blood mononuclear cells (PBMC) from B-CLL patients to assess the ability of PNA to down-regulate the expression of CD5 as intended." (PMID 35358273, 2022). "Autoreactive CD5+ B cells with restricted BCRs were shown to be the origin of CLL development in aging mice, in which chronic stimulation by autoantigens causing persistent inflammation adds to leukemia progression." (PMID 34417556, 2022). "Upon in vitro TLR stimulation with the agonist mix, 10 μM ND2158 induced a significant reduction in cell viability in CD19+CD5+ leukemia cells after 3 and 6 days of treatment, which was also confirmed by a decrease in intracellular ATP levels in the presence of 10 and 30 μM ND2158." (PMID 31197259, 2020). "Thus, we first assessed leukemia growth by flow cytometry using the marker CD5, which is highly expressed on CEM cells." (PMID 31043590, 2019). "CLL, characterized by an accumulation of CD5+ B lymphocytes in the peripheral blood, bone marrow, and lymphoid organs due to abnormal lymphocyte production in the bone marrow, is the most prevalent leukemia in adults, constituting nearly a third of all leukemia cases." (PMID 38675444, 2024). "Importantly, IgM–/– TCL1 mice possess a CD19+CD5+IgD+ B cell population from which the leukemia could initiate." (PMID 34813501, 2022). "Furthermore, analysis of CD45 + cells circulating in the blood demonstrated that a small subset (5/15 analyzed mice) of aged Eμ-XPO1WT, Eμ-XPO1E571G, and Eμ-XPO1E571K mice spontaneously developed a circulating leukemia characterized by expansion of CD5+/CD19+ and CD19+/B220dim B lymphocytes." (PMID 33451349, 2021). "Indeed, here we report overexpression of human MTCP1 restricted to the B cell compartment in mice produces a clonal CD5+/CD19+ leukemia recapitulating the major characteristics of human CLL and demonstrates favorable response to therapeutic intervention with ibrutinib." (PMID 34732719, 2021). "Immunohistology now showed a cell staining positive for CD20, CD3, CD5 and CD23 consistent with leukemia cutis." (PMID 39493706, 2024). "CD5, CD16, CD56, and CD57 were detected on tumor cells in γδT-LGL leukemia in 43% (6/14), 50% (7/14), 8% (1/13), and 64% (9/14) of cases, respectively." (PMID 39161592, 2024). "We previously observed that transgenic expression of TCL1+(TC+)Tg in ATA B cells induced CLL/leukemia in middle aged mice, which originated from TC+ZAP70–CD5+ or TC+ZAP70+CD5+(or CD5–) B1 cells." (PMID 38570827, 2024).
leukemia (continued). "Commonly referred to as the most frequent leukemia in the Western world, chronic lymphocytic leukemia (CLL) is a lymphoproliferative malignancy characterized by clonal expansion of CD19, CD23, and CD5-positive mature B-cells." (PMID 39376808, 2024). "A further strategy is to bridge allo-HSCT after achieving deep molecular remission with CD5/CD7 bispecific CAR-T therapy to reconstitute patients’ immune systems and subsequently achieve long-term leukemia-free survival." (PMID 35332132, 2022). "Monthly assessment of circulating CD5+/CD19+ and CD19+/B220dim leukemia cells in all treated mice displayed a lower leukemic burden at 6 and 12 months, contributing to considerable survival prolongation in mice receiving ibrutinib at 12 months of age." (PMID 34732719, 2021). "We tested the ability of CD5 CAR-T cells administered on days 4 and 7 post-engraftment to suppress leukemia progression." (PMID 34274536, 2021). "Starting at around day 100, TCL1 Nfat2−/− mice exhibited a significant acceleration of leukaemia proliferation as compared to controls with intact NFAT2 expression as documented by significantly increased lymphocytes and CD19+CD5+ CLL cells." (PMID 28970470, 2017). "Immunophenotypic data, available for 202 of the 210 patients, showed that all cases of leukemia were CD19+, 196/202 were CD5+, 188/202 were CD20+ [61/188 expressed (+) and 127/188 expressed (++)] and 200/202 were CD23+." (PMID 23599777, 2013). "Thus, ATAμκTg B lymphoma/leukemia can be generated from TC–ZAP70–CD5–, or TC–ZAP70+CD5+(or CD5–) B1 cells." (PMID 38570827, 2024). "Cells with lymphoid markers were also present in the transcriptionally defined leukemia cells, but in smaller proportions, including CD19+/CD22+/CD30+ cells (5.96%) CD19+/CD22+/CD45+ cells (5.49%), CD3+/CD5+/CD7+ cells (4.45%), and CD3+/CD4+/CD5+ cells (0.4%)." (PMID 39294124, 2024). "To evaluate the phenotype of neutrophils, we collected the spleens (SPL) of TCL1 leukemia-bearing mice at two stages of disease development: early (4–10% of leukemic CD5+ CD19+ cells detected in the blood) and late (50–80% of leukemic CD5+ CD19+ cells detected in the blood)." (PMID 37817276, 2023). "CD5 and CD7 expression on the surface of CD45+ cells in the peripheral blood of mice were measured using flow cytometry to assess the effect of CAR-T treatment on heterogeneous leukemia cells." (PMID 35332132, 2022). "All cases of T-PLL and primary SS showed CD5 expression, whereas 75% of T-LGL leukemia cases were negative or only weakly positive for CD5." (PMID 29262669, 2017). "B-chronic lymphocytic leukemia (B-CLL), the most common human leukemia, is characterized by predominantly non-dividing malignant mature CD5+ B lymphocytes with an apoptosis defect." (PMID 23555960, 2013). "Anti-CD5 mAb bound only to the T-cell line Jurkat and to the leukaemia cell line CD5+ JOK1-5.3, but not to the parental JOK1 cell line nor to the B lymphoma cell lines." (PMID 21504579, 2011). "Almost all of the lymphocytes expressed the CD19+CD5+ leukaemia phenotype and 0% and 10.1% were positive for CD1d (data not shown)." (PMID 22174854, 2011). "In the diagnosis of CLL, CD5, CD19, CD20, CD23, and surface or cytoplasmic kappa and lambda light chains are regarded as essential markers, and CD10, CD43, CD79b, CD81, CD200 and ROR1 as additional targets useful in the differential diagnosis from other small B-cell lymphomas/leukaemias." (PMID 35732829, 2022). "All mice treated with CD5 CAR-T and CD5CD7KO T cells progressed steadily, while CD7 CAR-T cells were able to temporarily inhibit neoplastic cells but failed to control the progression of leukemia due to the loss of CD7 antigen on tumor cells." (PMID 35332132, 2022). "However, complete eradication was not seen in these models and leukemia blasts retained CD5 cell surface expression, suggesting lack of persistence of CAR." (PMID 26484338, 2015).
leukemia (continued). "The flow cytometry results were consistent with CD5-negative, CD10-negative mature B-cell lymphoma/leukemia." (PMID 41574362, 2025). "The immunophenotype was characterized by positive Kappa, CD19, CD22, HLA-DR, and dim CD20 expressions and negative CD10, CD5, CD25, and CD33 expressions, consistent with CD5−CD10− mature B-cell lymphoma/leukemia." (PMID 41574362, 2025). "If leukemic cells have weak or negative CD5 at diagnosis and then lose intracellular CD3 at relapse, the leukemia should be reclassified as myeloid." (PMID 38891797, 2024). "In this setting, autonomous signaling and leukemia development did not occur, even though CD19+CD5+IgD+ B cells existed in these animals, suggesting that IgM expression is involved in the biased use of the specific IGHVs in B cells." (PMID 34813501, 2022). "In our case, however, the leukemia cells was found negative for CD2, CD5 and CD7, making aberrant expression of AML relatively unlikely." (PMID 22356850, 2012). "CD5 and CD7 expression was variable (bright, dim, or negative) on all or part of the T-LGL leukemia cells, whereas in 3 cases lymphocytes showed an absence of both antigens." (PMID 18474096, 2008). "Splenic B-cell lymphoma/leukemia with prominent nucleoli (SBLPN) is a new entity in the 5th edition of the WHO classification, which contains HCLv and also cases that were previously classified as CD5 negative B-cell prolymphocytic leukemia (B-PLL)." (PMID 37656249, 2023).
B-cell lymphoma (67 papers, 2011 to 2026). "Histological examination revealed a low-grade B-cell lymphoma (probable CD5-positive mucosa-associated lymphoid tissue (MALT) lymphoma, unclassifiable)." (PMID 41262807, 2025). "This was associated with a dense dermal infiltration of CD5-positive B-lymphoid cells consistent with his low-grade B-cell lymphoma." (PMID 26201725, 2015). "PET imaging demonstrated hypermetabolic lymphadenopathy, and bone marrow biopsy revealed infiltration by a CD5-/CD10- B-cell lymphoma consistent with SMZL." (PMID 41695001, 2026). "If a CD5+ B-cell lymphoma demonstrates an immunophenotype atypical for CLL/SLL and MCL, a CD5-positive MZL should be considered." (PMID 40075660, 2025). "Definitive biopsy with immunohistochemistry confirmed a high-grade B-cell lymphoma, positive for CD5 and demonstrating triple expression of Bcl2, Bcl6, and c-Myc." (PMID 40941668, 2025). "A biopsy of this mass was performed within a few days, and pathology and immunohistochemical examination confirmed the presence of a high-grade B-cell lymphoma, expressing CD5+ and showing triple expression of Bcl2, Bcl6, and c-Myc." (PMID 40941668, 2025). "While it is not completely specific, examination for the MYD88 L265P mutation is routine in clinical practice because the immunophenotype of LPL can overlap other B-cell lymphomas that lack expression of CD5 and CD10." (PMID 40075660, 2025). "We report a rare case of CD5-positive low-grade B-cell lymphoma in the subglottic region, representing an unusual immunophenotype at this site and resulting in airway stenosis necessitating tracheostomy." (PMID 41262807, 2025). "We present a rare case of low-grade B-cell lymphoma, presumed to be CD5-positive MALT lymphoma, in the subglottic region, which required emergent tracheostomy due to subglottic tracheal airway stenosis and was treated with BR chemotherapy." (PMID 41262807, 2025). "In our patient, FNA indicated abnormal cytology, and subsequent biopsy confirmed a high-grade B-cell lymphoma expressing CD5 and triple expression of Bcl2, Bcl6, and c-Myc." (PMID 40941668, 2025). "The rate of incidence of CD5 positivity is drastically decreased across the other subtypes of B-cell NHLs; however, the role of CD5 as a prognostic marker in these cancers has been extensively explored." (PMID 39410047, 2024). "CD5 is traditionally considered a T-cell marker and is expressed in certain types of B-cell lymphomas (BCLs)." (PMID 38535060, 2024). "Zanubrutinib is a BTK inhibitor reported to be effective for B‐cell lymphomas with MYD88 and CD79b mutations, double expression of MYC and BCL2/BCL6, and CD5 expression." (PMID 39054569, 2024). "The most represented aberrancies were: CD5-, CD4-CD8-, and CD3- in T-NOS lymphomas, CD21+, CD4-CD8-, and CD3- in TZLs, and CD34+, CD44-, and CD5+ in B-cell lymphomas." (PMID 35448684, 2022). "Further studies are needed to assess the prognostic value of CD5 expression and loss of CD44 in old dogs with B-cell lymphoma." (PMID 35448684, 2022). "This interesting field is still developing and the benign analogues of CD5+ B cell lymphomas and the existence of human B1 cells are likely to gain resolution in the near future." (PMID 36370126, 2022). "Concerning B-cell lymphomas, CD34 expression, loss of CD44, and expression of CD5 were the most represented aberrancies in our caseload." (PMID 35448684, 2022). "Most cases of the B cell lymphomas of small lymphocytic lymphoma and mantle zone lymphoma appear to be derived from immature B cells that also express CD5." (PMID 36370126, 2022). "In conclusion, the appropriate morphological and clinical context assisted by flow cytometry panels and/or immunohistochemistry allows the differential diagnosis of CD5-positive, non-Hodgkin, B-cell lymphomas involving the spleen." (PMID 34898558, 2021). "BLV infected animals with high levels of PVL is most likely to develop malignant CD5+ B-cell lymphoma." (PMID 33804456, 2021).